TACC1 (transforming acidic coiled-coil containing protein 1)
Description:
Involved in transcription regulation induced by nuclear receptors, including in T3 thyroid hormone and all-trans retinoic acid pathways. Might promote the nuclear localization of the receptors. Likely involved in the processes that promote cell division prior to the formation of differentiated tissues.
Synonyms: Ga55
Tractability: PROTAC: ubiquitination databases record sites on it; its protein half-life has been measured.
Gene: Protein-coding gene on chromosome 8 (38,728,166 to 38,853,028, forward strand). Ensembl gene ENSG00000147526.
Subcellular location: Cytoplasm; Nucleus; Cytoplasm, cytoskeleton, microtubule organizing center, centrosome; Midbody; Membrane (Isoform 5); Cytoplasm (Isoform 10)
Subcellular location (Human Protein Atlas): Cytosol
Gene Ontology:
Molecular function: nuclear estrogen receptor binding; nuclear glucocorticoid receptor binding; nuclear receptor binding; nuclear retinoic acid receptor binding; nuclear retinoid X receptor binding; nuclear thyroid hormone receptor binding; peroxisome proliferator activated receptor binding; protein binding; transcription coactivator activity
Biological process: astral microtubule organization; cerebral cortex development; nuclear migration; mitotic spindle organization; positive regulation of DNA-templated transcription
Cellular component: cytoplasm; midbody; nucleus; cytosol; centrosome; membrane
Genetic constraint (gnomAD): Loss-of-function variants: 41 observed, 70.16 expected, observed/expected ratio (o/e) 0.58, 90% interval 0.45 to 0.76. The upper end of that interval is the gene's LOEUF score, 0.76, which puts it in group 3 of 6, group 1 being the genes least tolerant of losing a copy. Missense variants: 887 observed, 951.07 expected, observed/expected ratio (o/e) 0.93, 90% interval 0.88 to 0.99. Synonymous variants: 363 observed, 376.63 expected, observed/expected ratio (o/e) 0.96, 90% interval 0.88 to 1.05.
Homologues: Orthologues: chimpanzee TACC1 (99% identical), macaque TACC1 (86% identical), dog TACC1 (85% identical), rabbit TACC1 (80% identical), guinea pig TACC1 (77% identical), mouse Tacc1 (74% identical), rat Tacc1 (73% identical), zebrafish tacc1 (42% identical), Drosophila melanogaster tacc (21% identical). Paralogues in human: TACC2 (39% identical), TACC3 (21% identical).
Diseases named in the same sentence as TACC1 in open-access papers:
TACC1 is named in the same sentence as 51 diseases in open-access papers, as found by Europe PMC text mining. Sharing a sentence is not in itself a finding about the gene and the disease. The quoted sentences say what the papers report.
breast carcinoma (12 papers, 2006 to 2023). "Recent studies have shown that dysregulation of TACC1 seems to be associated with the occurrence of multiple malignancies, such as rhabdomyosarcoma, breast cancer, gastric cancer, leukaemia and ovarian cancer." (PMID 34897285, 2021). "One of the other candidates identified in this screen, TACC1, has been shown to enhance mammary tumor formation induced by heterozygous PTEN loss in vivo and was shown to mediate cell survival following PI3K pathway inhibition induced by PTEN over expression." (PMID 28561737, 2017). "Previous studies have also demonstrated that TACC1 was involved in endocrine therapy (tamoxifen and fulvestrant) resistance in breast cancer 27 and TACC3 was associated with chemoresistance (paclitaxel) in uterine cervical cancer." (PMID 27333920, 2016). "Dysregulation of the human transforming acidic coiled-coil (TACC) protein is associated with the development and progression of breast cancer, where both TACC1 and TACC2 bind to YEATS4 to form complexes that affect the growth and proliferation of breast cancer cells." (PMID 37435030, 2023). "The gene TACC1 is associated with endocrine therapy resistance in breast cancer." (PMID 29312626, 2017). "Abnormal TACC1 regulation plays an important role in the occurrence and development of multiple myeloma including breast cancer, gastric cancer, and ovarian cancer." (PMID 35111672, 2021). "For instance, TACC1 was an estrogen‐regulated gene 6 and its amplification was correlated with decrease in survival duration or distant recurrence in breast cancer." (PMID 27333920, 2016). "Human TACC genes were initially described as potential cancer genes and are all present in genomic regions that are rearranged in certain cancer cells, TACC1 having been first discovered as the product of an amplicon in breast cancer." (PMID 20078863, 2010). "It is worth noting that alterations in TACC1 have been found in breast cancers, a type of tumour whose development is known to be controlled by estrogen receptors." (PMID 20078863, 2010). "Since we found TACC1 underexpressed in the majority of breast carcinoma, TACC1 role remains to be determined." (PMID 17137506, 2006). "Interestingly, TACC1 can form a complex with aurora kinase A, which controls translation and cell division in breast cancer." (PMID 37370789, 2023). "Additionally, TACC1 and YEATS4 regulate the expression of downstream target genes and accelerate breast cancer malignancy." (PMID 37435030, 2023). "Interestingly, the TACC1 isoforms expressed in human breast cancer cells do not interact with the histone acetyltransferase pCAF, although all human TACC proteins can directly interact with this histone acetyltransferase in vitro." (PMID 34897285, 2021).
gastric cancer (4 papers, 2002 to 2021). A primary or metastatic malignant neoplasm involving the stomach. "This may in part be explained by as yet unidentified tissue specific functions of these proteins or the existence of cancer-associated alternative splice products, as evidenced for TACC1 in gastric cancer." (PMID 15918899, 2005). "The expression of a newly identified TACC1 isoform is restricted to brain and gastric cancer tissues." (PMID 12087473, 2002). "Interestingly, TACC1 and TACC2 have also have been detected by SEREX in gastric cancer by Yuichi Obata (SEREX database)." (PMID 12087473, 2002).
ovarian carcinoma (4 papers, 2005 to 2023). A malignant neoplasm originating from the surface ovarian epithelium. "In a recent study, TACC1 was found to be up-regulated and act as an oncogene in breast and ovarian cancers." (PMID 24358147, 2013). "SAGE (Serial Analysis of Gene expression) analysis further suggests that TACC3 and TACC1 are downregulated in ovarian tumors and ovarian cancer cell lines." (PMID 15918899, 2005). "These techniques have indicated that deletions or rearrangements of 4p16 and 8p11, the loci for TACC3 and TACC1 respectively, commonly occur in 40% of ovarian cancer cell lines and primary tumors from both familial and sporadic cases." (PMID 15918899, 2005). "TACC1 is involved in several cancers including breast and ovarian cancers and leukemia." (PMID 24358147, 2013). "However, a recent serial analysis of gene expression (SAGE) suggested that TACC1 was down-regulated in ovarian tumors and ovarian cancer cell lines." (PMID 24358147, 2013). "Thus, based upon both the location of TACC1 and TACC3 in regions consistently associated with ovarian cancer and SAGE expression data, we have set out to determine the occurrence of alterations of these TACCs in ovarian cancer." (PMID 15918899, 2005). "Researchers have examined how TACC1 functions as a regulator in breast and ovarian cancers; however, there has not been a separate report on THCA." (PMID 37907864, 2023).
gastrointestinal stromal tumor (2 papers, 2023 to 2025). "Recently, FGFR::TACC fusions have been reported in a variety of non-epithelial cancers, including FGFR1::TACC1 fusions as a novel alternative genetic driver in rhabdomyosarcoma, and FGFR2::TACC2 fusions as a mechanism of multidrug resistance in TKI-treated gastrointestinal stromal tumors (GIST)." (PMID 39387893, 2025).
melanoma (2 papers, 2020). A malignant, usually aggressive tumor composed of atypical, neoplastic melanocytes. "TACC1 mutations were first reported in a WES study of 121 melanoma tumor/normal pairs reporting five novel melanoma candidate genes, including TACC1, with a frequency of 7% which was confirmed in a further similar study of 25 metastatic/germline pairs." (PMID 32850962, 2020). "Finally, in a recent study several key genes involved in melanomagenesis, including TACC1, in 115 human melanoma cell lines, 248 patient-derived xenografts, 31 cell lines derived from PDX, and 68 patient tumors, an overall frequency rate of 1.47% was reported." (PMID 32850962, 2020).
ovarian tumors (2 papers, 2005 to 2013). "We have now shown that 78.5% of ovarian tumors lack appreciable expression of TACC1 and/or TACC3 proteins, confirming the inferences made from published SAGE analysis." (PMID 15918899, 2005). "Within the ovarian tumor set tested (n = 65), there was a significant difference in the expression of TACC1 compared to TACC3 (Fisher's exact test, p = 0.0008)." (PMID 15918899, 2005). "The result of our multivariate analysis showed that TACC1 over-expression was an independent prognostic factor of GC, which is consistent with the earlier finding on the prognostic significance of TACC1 observed in ovarian tumors." (PMID 24358147, 2013). "This has revealed that 78.5% of ovarian tumors lack appreciable expression of TACC1 and/or TACC3." (PMID 15918899, 2005). "Recent, large-scale genomic analysis and Serial Analysis of Gene Expression data suggest that TACC1 and TACC3 may also be involved in the etiology of ovarian tumors from both familial and sporadic cases." (PMID 15918899, 2005). "Published SAGE (Serial Analysis of Gene Expression) analysis suggests that TACC1 expression is absent in 3 out of 7 bulk ovarian tumors and cell lines." (PMID 15918899, 2005).
acute GVHD (1 paper, 2018). "ACC1-deficient T cells (TACC1) are less pathogenic than WT T cells during autoimmune encephalomyelitis and in a lethal model of acute GVHD, where they permitted survival of recipient mice." (PMID 29675017, 2018).
breast tumours (1 paper, 2010). "It is interesting that TACC1 has been recognized as the strongest prognostic marker associated with endocrine therapy resistance in breast tumours." (PMID 20078863, 2010).
clear cell carcinomas (1 paper, 2005). "The distribution pattern of expression of the two TACC proteins was different, with TACC3 loss being more common in serous papillary carcinoma compared with clear cell carcinomas, while TACC1 staining was less frequent in endometroid than in serous papillary tumor cores." (PMID 15918899, 2005).
clear cell ovarian tumor (1 paper, 2005). "In contrast, TACC1 was detected in 71.4% (30 of 42) serous papillary, 60% (3 of 5) mucinous, 28.6% (2 of 7) endometroid and 54.5% (6 of 11) clear cell ovarian tumor cores." (PMID 15918899, 2005).
embryonic carcinoma (1 paper, 2010). "We found that F9 embryonic carcinoma cells expressed fairly high levels of endogenous TACC1." (PMID 20078863, 2010).
Erythema (1 paper, 2023). Redness of the skin, caused by hyperemia of the capillaries in the lower layers of the skin. "However, by day 3, IMQ-treated TACC1 mice showed significantly less erythema than IMQ-treated WT mice." (PMID 37594540, 2023). "After two days of IMQ treatment, both WT and TACC1 mice developed erythema and scaling." (PMID 37594540, 2023). "TACC1 mice showed significantly lower scores at the peak of inflammation due to considerably reduced erythema and skin thickness, although no significant changes in scaling were observed compared to the IMQ-treated WT mice." (PMID 37594540, 2023).
head and neck squamous cell carcinoma (1 paper, 2021). A squamous cell carcinoma that arises from any of the following anatomic sites: lip and oral cavity, nasal cavity, paranasal sinuses, pharynx, larynx, and salivary glands. "However, the expression and biological functions of TACC1 variants in head and neck squamous cell carcinoma (HNSCC) remain unclear." (PMID 34897285, 2021).
hypoplastic left heart syndrome (1 paper, 2024). Hypoplastic left heart syndrome (HLHS) refers to the abnormal development of the left-sided cardiac structures, resulting in obstruction to blood flow from the left ventricular outflow tract. "As for another gene, TACC1 (Transforming Acidic Coiled-Coil Containing Protein 1, 605301), it has been shown to be associated with CHD but the association between such gene with HF-hypoplastic left heart syndrome has not been detailed and confirmed." (PMID 39202774, 2024).
liver cancer (1 paper, 2021). An epithelial or non-epithelial malignant neoplasm that arises from the liver. "Our research demonstrated that the methylation status of the TACC1 promoter region is significantly related to promoter activity, which implies the new roles of TACC1 in liver cancer." (PMID 35111672, 2021).
lobular carcinomas (1 paper, 2010). "The initial description of TACC1 comes from the study of an amplicon associated with ER-positive lobular carcinomas that metastasize to axillary lymph nodes." (PMID 20078863, 2010).
lung adenocarcinoma (1 paper, 2023). A carcinoma that arises from the lung and is characterized by the presence of malignant glandular epithelial cells. "TACC1 was identified to be different in lung adenocarcinoma, lung squamous cell carcinoma, and COPD patients." (PMID 37821974, 2023).
lymph node metastasis (1 paper, 2013). "Multivariate analysis showed that lymph node metastasis and TFF3 and TACC1 over-expression were independent prognostic factors." (PMID 24358147, 2013). "Age, lymph node metastasis, and TFF3 and TACC1 over-expression were significantly correlated with low survival (P<0.05, P<0.05, P = 0.005 and P = 0.009, respectively)." (PMID 24358147, 2013). "Univariate analyses showed that age, lymph node metastasis, TFF3 over-expression and TACC1 over-expression were significantly correlated with a short survival time." (PMID 24358147, 2013). "Multivariate analysis showed that lymph node metastasis and the expression of TFF3 and TACC1 in tumor epithelial cells were independent prognostic factors for overall survival, and that the hazard ratio (HR) of tumor-related death increased by 3.409 fold in FF3 group (P<0.001; 95% CI 2.387–8.143)." (PMID 24358147, 2013).
neurocytomas (1 paper, 2025). "Regarding molecular studies, the FGFR1: TACC1 fusion in neurocytomas is an essential molecular alteration due to its impact on the clinical implications." (PMID 40677455, 2025). "This classification was reinforced by the detection of FGFR1: TACC1 fusion, which is a molecular marker which is characteristic of neurocytomas." (PMID 40677455, 2025). "The identification of FGFR1: TACC1 fusions in neurocytomas could provide, in the future, a targeted treatment strategy which may be more effective than traditional therapeutic options." (PMID 40677455, 2025).
oligodendroglioma (1 paper, 2023). A well-differentiated (WHO grade II), diffusely infiltrating neuroglial tumor, typically located in the cerebral hemispheres. "Other interesting alterations involving FGFR1 detected in this series of tumors were two FGFR1::TACC1 fusions found in one anaplastic PA (P4551_218T) and one oligodendroglioma (P7708_105T)." (PMID 37221626, 2023).
prostate adenocarcinoma (1 paper, 2010). "For example, it has been described that in the normal human prostate tissue TACC1 is located in the nucleus whereas it is cytoplasmic in prostate adenocarcinomas." (PMID 20078863, 2010).
prostate carcinoma (1 paper, 2006). A carcinoma that arises from epithelial cells of the prostate gland. "FGFR1, TACC1 and WT1 gene expression levels were associated with the androgen-independent stage in xenografts and human prostate carcinoma samples." (PMID 17137506, 2006). "We observed upregulation of TACC1 expression in prostate carcinoma." (PMID 17137506, 2006). "We then assessed the expression of four candidate proteins – FGFR1, MART1, TACC1 and WT1 – in human prostate carcinoma samples by IHC." (PMID 17137506, 2006). "We found that expression of FGFR1, WT1, and, to a lesser extent, TACC1 protein is upregulated in advanced stages (pT3 and/or N1/M1) of prostate cancer, whereas MART1 is mainly expressed in localized (pT2) stage prostate cancer." (PMID 17137506, 2006). "Using three methods of analysis (DNA microarrays, TMA, and RT-PCR), we have shown that FGFR1, TACC1 and WT1 have much higher levels of expression in human prostate carcinoma than in benign prostate tissue samples, at both mRNA and protein levels." (PMID 17137506, 2006). "In this study, we identified four candidate genes – FGFR1, MART1, TACC1 and WT1 – by gene expression profiling of different stages of prostate carcinoma in an animal model." (PMID 17137506, 2006). "In the same way, we observed that the corresponding mRNAs – FGFR1, TACC1, and WT1 on the one hand, and MART1 on the other hand – are overexpressed in HR and HS stage LuCaP 23.1 prostate carcinoma, respectively." (PMID 17137506, 2006). "Expression of FGFR1, MART1, TACC1 and WT1 proteins in human prostate cancer." (PMID 17137506, 2006).
psoriasis (1 paper, 2023). An autoimmune condition characterized by red, well-delineated plaques with silvery scales that are usually on the extensor surfaces and scalp. "Upon psoriasis development, TACC1 mice maintained higher frequencies of effector Tregs and limited IFN-γ-producing Th1/Tc1 in skin-draining LNs." (PMID 37594540, 2023). "During psoriasis induction, TACC1 mice maintained significantly higher proportions of activated CD44+CD25+ Tregs and effector CD62L-CD44+ Tregs in skin-draining LNs." (PMID 37594540, 2023). "We observed that effector Treg frequencies were remarkably increased in TACC1 mice under homeostasis and maintained during psoriasis development." (PMID 37594540, 2023). "Those effector phenotypes could grant them the capacity to respond rapidly to tissue damage and immune-mediated inflammation such as psoriasis induction as we observed in the IMQ-treated TACC1 mice." (PMID 37594540, 2023).